CD34 (CD34 molecule)
Diseases named in the same sentence as CD34 in open-access papers (continued):
Sharing a sentence is not in itself a finding about the gene and the disease.
pancreatic cancer (20 papers, 2011 to 2025). "In a humanized CD34+ NSG mouse xenograft model for pancreatic cancer, tumors in mice treated with SIWA318H grew significantly slower compared to those in control mice (p < 0.001)." (PMID 37805542, 2023). "Using the obtained antibody, mouse LAT1 was detected in CD34-positive endothelial cells in the tumors of pancreatic cancer MIA PaCa-2 cells and of non-small cell lung cancer H520 cells." (PMID 33256804, 2020). "Pancreatic cancer cell lines displayed either the fully or the partially permissive phenotype, while the partially permissive phenotype was also observed in CD34+ cord blood cells." (PMID 28031367, 2017). "The present research aimed to investigate the ability of pancreatic carcinoma cells to attract and skew the differentiation of CD34+ progenitor cells toward endothelial cells, by releasing pro-angiogenic factors." (PMID 24341512, 2013). "Immunohistochemistry (IHC) was performed to detect IL-17+ cells in 46 pancreatic tumor tissues, as well as expression of CD34 in 24 tumor tissues." (PMID 22174607, 2011). "However, we anticipated challenges in obtaining a sufficient number of CD34 + cells from pancreatic cancer patients, which made it difficult to generate enough murine avatar models for all treatment groups." (PMID 39773310, 2025). "To generate HLA-matched MHC-II+ cell lines for these studies, we transduced the KRASG12V+ cell lines NCI-H2444 and DAN-G, derived from human lung and pancreatic cancers, respectively, with CIITA and a construct encoding HLA-DRB5*01:01 with a truncated CD34 reporter gene." (PMID 36512410, 2023). "To determine whether VM structures could be observed in tissues obtained from 70 pancreatic cancer patients, we utilized anti-CD34 and PAS staining to identify the endothelium and VM channels, respectively." (PMID 28599281, 2017). "Indeed TLR7, TLR8 and CD34 were positively expressed in pancreatic cancer and pancreatic cells from chronic pancreatitis cells, but not or at very low levels in normal pancreatic cells." (PMID 26134824, 2015). "This study demonstrates the ability of pancreatic carcinoma cells to attract CD34+ cells to the tumor site, and to interfere with those cells' hematopoietic development, by diverting their differentiation toward endothelial cells; these cells can become a component of the tumor vasculature." (PMID 24341512, 2013). "In addition, TQ could significantly inhibit the metastasis of pancreatic cancer in tumor-bearing mice and downregulate the positive expression of CD34, NF-κB, and MMP-9 in pancreatic tumors." (PMID 36686732, 2022). "In this paper, we present a strategy for engineering CD34+ cells to derive mDCs, overexpressing CD93, CD40L, and CXCL13, followed by antigen pulsing for enhanced targeting of pancreatic tumors." (PMID 40733726, 2025). "However, the functional roles of CD34 in pancreatic cancer remain unclear." (PMID 32586050, 2020).
Splenomegaly (20 papers, 2012 to 2025). Abnormal increased size of the spleen. "Median time to neutrophil engraftment ≥0.5x109/l was +20 days post-transplant and associated with BM fibrosis, splenomegaly and infused CD34+ cell number." (PMID 37637037, 2023). "All other factors, namely platelet count, TLC, PB and BM blast %, BM cellularity and lymphocyte%, IPT, lymphadenopathy, hepatomegaly, splenomegaly, molecular genetics, cytogenetic risk stratification, CD34+, CD34+/CD38-, CD4+/CD3+, CD8+/CD3+, CD4/CD8 ratio and MRD had no impact on PFS." (PMID 40940644, 2025). "Risk factors for primary PGF include a low dosage of CD34+ cell infusion, donor‐specific antibodies, GVHD, CMV infection, iron overload, and splenomegaly." (PMID 36992548, 2023). "Among these, high levels of LINC01268, MALAT1 or GAS5 correlate with detrimental clinical variables, such as high count of leukocytes and CD34+ cells, severe grade of bone marrow fibrosis and presence of splenomegaly." (PMID 34638230, 2021). "In comparison with ET, patients with prePMF had higher leukocyte count, lower hemoglobin level, higher platelet count, higher LDH values, and higher number of circulating CD34-positive cells; they showed more frequently splenomegaly (all P values < ·001)." (PMID 29254200, 2017). "In turn, IL-6 plasma levels correlated with BM fibrosis (p = 0.0056; r = 0.49), splenomegaly (p = 0.018; r = 0.46), and the number of circulating CD34+ cells (p = 0.029; r = 0.48) and correlated negatively with hemoglobin values (p = 0.047; r = −0.39)." (PMID 27672242, 2016). "Finally, analysis for expression of the hematopoietic stem cell markers CD34, c-kit and Sca-1 showed that while c-kit expression remained mostly undetectable, Sca-1 and CD34 were expressed at high levels in mice with splenomegaly." (PMID 23985023, 2013). "Since the primary cause of splenomegaly in PMF is extramedullary hematopoiesis (EMH) resulting from abnormal mobilization of CD34+ hematopoietic stem/progenitor cells (HSPCs), we analyzed whether EDA-FN plasma levels were associated with circulating CD34+ HSPC frequency." (PMID 36212480, 2022). "The percentage of CD34+CD38- stem cells at diagnosis was correlated significantly to clinical scores, WBCs count, BM blast cells %, splenomegaly, and BCR-ABL %." (PMID 34711000, 2021). "PMF BM-derived CD14+/CD34- monocytes engrafted and induced a PMF-like phenotype with splenomegaly, myeloid hyperplasia with clusters of atypical megakaryocytes, persistence of the JAK2V617F mutation, and BM and spleen fibrosis." (PMID 31569199, 2019). "More importantly, c-MYChighMYCBP2low patients showed higher median WBC counts, higher percentage of CD34(+) and CD33(+) cells, higher rate of splenomegaly, liver infiltration, increased LDH, and lower CR rate compared with that of c-MYClowMYCBP2high patients." (PMID 26517351, 2015). "Patients with high c-MYC expression and/or low MYCBP2 expression had higher WBC counts and a higher percentage of CD34+ or CD33+ cells, as well as splenomegaly, liver infiltration, higher BM blasts, and lower CR rate." (PMID 26517351, 2015). "Serial transplantation of 1 500 CD34+CD2+CD7+Lin− cells sorted from a NOTCH1Mutated T-ALL (Patient 05) sample resulted in marked thymic enlargement, splenomegaly and pale marrows indicative of robust leukemic engraftment." (PMID 22768113, 2012). "In particular, high levels of LINC01268, GAS5 and MALAT1, correlated with detrimental features of MF, such as high WBC count, increased number of circulating CD34+ cells, marked LDH activity, presence of splenomegaly and a more severe grade of bone marrow fibrosis." (PMID 34638230, 2021). "Besides EDA-FN, three variables at diagnosis were significantly correlated with splenomegaly progression: WBC >12x109/L (HR = 3.73; 95% CI, 1.09-12.82; P=0.036), CD34+ blood cells > 50 x106/L (HR = 11.11; 95% CI, 1.95-58.82; P=0.006), and spleen size (HR = 1.03; 95% CI, 1.01-1.04; P=0.001)." (PMID 36212480, 2022).
COVID-19 (19 papers, 2021 to 2025). A disease caused by infection with severe acute respiratory syndrome coronavirus 2. "CD34 expression was lower in the COVID-19 group (p = 0.048), while CD4, CD68, and vimentin levels were higher in the COVID group (p < 0.05)." (PMID 39057113, 2024). "The expression of CD34+, representative of the vascular endothelium, was lower in the COVID-19 group, suggesting the presence of blood vessel injuries related to SARS-CoV-2." (PMID 39057113, 2024). "Considering the potential effect of COVID-19 on grafts, we compared CD34+ cells and MNC of grafts derived from COVID-19 positive, experienced and negative donors." (PMID 39077735, 2024). "The frequency of Lin-CD34+DNAM-1bright cells was also compared to COVID-19 or to chronic HIV-1 patients, where relevant increases in circulating inflammatory CLP occur." (PMID 38390333, 2024). "The colocalization ratio between Hsp60 and CD34 was significantly increased in the COVID-19 group compared to the control group (p = 0.0192)." (PMID 34831356, 2021). "A phase 1 study is assessing the efficacy and safety of CYNK-001 cells, which are allogeneic, off-the-shelf, and cryopreserved NK cells derived from CD34+ human placental stem cells, in 14 adult patients with mild to moderate COVID-19 (NCT04365101)." (PMID 34380619, 2021). "The immunohistochemical experiments for CD34 carried on COVID-19 lung tissue showed vascular congestion and increased microvascular texture." (PMID 34831356, 2021). "We showed that the MS1 cell state was induced in CD34+ human hematopoietic stem and progenitor cells (HSPCs) in vitro after incubation with plasma from patients with bacterial sepsis or severe COVID-19." (PMID 34103408, 2021). "Flow cytometric dot plot analysis showed that the frequency of Lin-CD34+DNAM-1brightCXCR4+ cells was considerably increased in COVID-19 patients compared to HIV-1 patients (who have increased frequencies of these circulating precursors)." (PMID 33861802, 2021). "We found that SARS-CoV-2 spike protein was present in CD34+ endothelia at blood–air barrier or pulmonary vessels in serial sections of the COVID-19 lungs, raising the possibility that SARS-CoV-2 was able to infiltrate blood–air barrier for intrapulmonary and systemic dissemination." (PMID 34135479, 2021). "Hence, therapy with CD34+ cells could prove feasible for promoting vascular growth in the lungs of patients with COVID-19 suffering from significant pulmonary damage (NCT04522817)." (PMID 34380619, 2021). "Secondly, altered hematopoiesis is evident in the peripheral circulation with megakaryocyte-primed gene expression in the earliest CD34+CD38+ HSPCs, and expanded megakaryocyte progenitors in the response to COVID-19." (PMID 33879890, 2021). ",37, 38, 39 Accordingly, PTBP1 knockdown in primary CD34 cells treated with erythropoietin (EPO) resulted in the detection of OS/TS chimeras, which were also shown to have a significant correlation with asymptomatic disease status in COVID-19 patients." (PMID 40110491, 2025). "Consistent with our results, a study with 16 COVID-19 positive donor and 55 COVID-19 negative donor reports that CD34+ and MNC dose were comparable among these participants." (PMID 39077735, 2024). "Non-inflammatory changes in the myocardium in patients with COVID-19 also included a weak lymphocytic infiltration in patients with respiratory distress syndrome, infiltration with a small number of monocytes and CD34-positive cells and interstitial fibrosis." (PMID 35177093, 2022). "We observed a scant quantity of non-organized endothelial cells in all thrombi, without differences between COVID-19 and control groups (respectively, median CD34+ area over total thrombus area = 0.23%, [IQR 0.12–0.71] vs. 0.37%, [IQR 0.10–0.95], p = 0.86)." (PMID 35105380, 2022).
COVID-19 (continued). "However, the small numbers of CD34 + cells in the PBMC fraction of COVID-19 patients and the lack of CD14 + cells in this subset suggest no interference with our results for CD14 + CD15- cells, isolated with our method." (PMID 36443794, 2022). "To test this hypothesis, we added plasma from patients with urosepsis or COVID-19 or from corresponding healthy controls, to CD34+ HSPCs or CD34+ HSPCs lacking the IL-6 receptor and observed a marked reduction in CD14+ cell production in the latter group." (PMID 34103408, 2021).
Immunodeficiency (19 papers, 2010 to 2024). Failure of the immune system to protect the body adequately from infection, due to the absence or insufficiency of some component process or substance. "Autologous genetically engineered CD34+ cells are used to treat patients with inherited monogenetic immune deficiencies such as chronic granulomatous disease and severe combined immune deficiency." (PMID 32384903, 2020). "Transplantation of human cord blood-derived Flk-1+/CD34+ cells could salvage ischemic tissue in severe combined immune deficiency mice." (PMID 20860813, 2010). "Gene therapy for immunodeficiencies is commonly performed by inserting a normal copy (native or codon optimized) of the defective gene into the patient’s CD34+ enriched HSPCs isolated from bone marrow (BM) or mobilized peripheral blood (mPB)." (PMID 33584681, 2020). "While CD34+ stem cells have shown significant progress in treating blood and immune disorders, recent studies suggest that CD34 markers may also be present on cancer stem cells (CSCs) and promote tumor recurrence and metastasis." (PMID 37241170, 2023). "Endocan and CD34+ progenitor cells might be suggested as potential additional markers of health, and disease status in immune disease, including systemic sclerosis." (PMID 34064667, 2021). "Methods: 128 rats were used in the study, including 38 in a pharmacological experiment on a model of stencil wounds and 90 in an experiment that studied the effect of spray on the number of CD34 cells in the blood of rats with chemically induced immunodeficiency." (PMID 32665909, 2020). "To overcome these deficiencies, we investigated S. aureus infection in non-obese diabetic (NOD)/severe combined immune deficiency (SCID)/IL2rγnull (NSG) mice engrafted with human CD34+ umbilical cord blood cells." (PMID 26618545, 2015). "A humanized mouse model generated with non-obese diabetic (NOD)/severe combined immune deficiency (SCID)/IL2rγnull (NSG) mice has now become one of the favored models for host–pathogen interactions, as these mice accept human hematopoietic cells (CD34+) and s mimic human immune system." (PMID 35052714, 2021). "In a second small study, 5 children with combined immunodeficiency and chronic viral infections received a combination of a CD34+ selected product and the CD45RA-depleted fraction of the CD34-negative product with post-HCT prophylaxis consisting of Cyclosporine and MMF." (PMID 32117310, 2020).
aplastic anemia (18 papers, 2009 to 2025). Anemia resulting from bone marrow failure (aplastic or hypoplastic bone marrow). "Previous studies have demonstrated an association between HLA-B*40:02 and acquired aplastic anemia, where the auto-antigen presentation caused a T-cell-mediated cytotoxicity, and in consequence, allele-expressing CD34+ cells were eliminated." (PMID 31575081, 2019). "In summary, we report a novel hereditary T1129P TERT mutation that leads to DKC with aplastic anemia that can be attributed to a severe reduction and functional impairment of CD34+ hematopoietic stem cells." (PMID 26546739, 2015). "Increased apoptosis of BMMNCs and/or CD34+ cells plays a major role in the pathogenesis of aplastic anemia patients." (PMID 32256652, 2020). "We therefore compared the gene expression profile of dnMpl LSK cells with expression profiles from CD34+ cells of patients with severe aplastic anemia (SAA) and refractory cytopenia (RC) published by Fischer and colleagues." (PMID 26147434, 2015). "We further compared gene expression profiles in LSK cells of dnMpl mice with human CD34+ cells of aplastic anemia patients and identified similar deregulations of important stemness genes in both cell populations." (PMID 26147434, 2015). "Expression of GATA-2 mRNA in purified CD34-positive cells was significantly decreased in aplastic anemia compared with normal subjects when examined by immunocytochemical analysis." (PMID 25619630, 2015). "IL-15 on fibroblasts from human spleen regulates NK cell differentiation from blood CD34+ progenitors and IL-15 on bone marrow fibroblast-like stromal cells contributes to T cell recruitment and expansion in aplastic anemia." (PMID 22792388, 2012). "Although GATA-2 expression was reported to be decreased in CD34-positive cells in aplastic anemia, many questions remain regarding the intrinsic characteristics of hematopoietic stem cells in this disease." (PMID 23028422, 2012). "With the exception of the patient with severe aplastic anemia, we were able to demonstrate that the higher the number of CD34+ cells was, the earlier the engraftment took place." (PMID 19466289, 2009). "We next detected Anapc2-expression in the CD34+ HSPCs of patients with aplastic anemia." (PMID 28968996, 2017). "CD34+ cells were markedly decreased in the bone marrow and Anapc2-expression in the residual CD34+ cells was undetectable, suggesting that APC/C was deficient and might have a relationship with the pathogenesis of aplastic anemia." (PMID 28968996, 2017). "Furthermore, we assessed GATA-2 and HOXB4 expression in CD34-positive cells from patients with aplastic anemia (n = 10) and idiopathic thrombocytopenic purpura (n = 13), and demonstrated that the expression levels of HOXB4 and GATA-2 were correlated in these populations (r = 0.6573, p<0.01)." (PMID 23028422, 2012). "The authors sequentially analyzed 10 patients with severe aplastic anemia (SAA) and used single-cell RNA-Seq of Lin–CD34+ sorted bone marrow cells." (PMID 39207851, 2024). "Aplastic anemia and PNH were characterized by a high proportion of CD56+ cells among CD34+ precursors and neutrophils." (PMID 39544295, 2024). "High expression IFN-γ of TNF-β in the bone marrow cells of aplastic anemia patients can accelerate NOS2 expression of CD34+ cells and result in the apparent increase in CD34+ cell apoptosis rate." (PMID 29736233, 2018). "High expression of interferon-γ (IFN-γ) or tumor necrosis factor-β (TNF-β) in patients with aplastic anemia can accelerate NOS2 expression in CD34+ cells and may increase the apoptosis rate of CD34+ cells." (PMID 29736233, 2018).